CCND1 (cyclin D1)
Diseases named in the same sentence as CCND1 in open-access papers (continued):
Sharing a sentence is not in itself a finding about the gene and the disease.
sarcoma (36 papers, 1995 to 2025). A usually aggressive malignant neoplasm of the soft tissue or bone. "ISG15 and IF16 are directly linked together but through PCNA and then through CCND1 they connect indirectly to the common to all sarcomas’ major hubs FGF2 and IL-6." (PMID 34359782, 2021). "Furthermore, in ALS, fused in sarcoma/translocated in sarcoma (FUS/TLS) protein acts as an RNA binding protein that is able to be recruited by a lncRNA to the genomic locus encoding cyclin D1, where it represses cyclin D1 transcription." (PMID 24970022, 2014). "For instance, CCND1 amplifications were observed in sarcoma (SARC) PDXs, which match the trial drug palbociclib." (PMID 34429404, 2021). "Unfortunately, no specific immunohistochemical marker is available for this tumor type, with the exception of cyclin D1, which seems to distinctly and selectively decorate this sarcoma." (PMID 32316524, 2020). "Synovial sarcoma samples (n = 43) were immunohistochemically stained for β-catenin, cyclin D1, p16, p21, p27, Rb, and phospho-Rb." (PMID 27334220, 2016). "The sarcomas expressing β-catenin or cyclin D1 also had a significantly higher Ki67 index (2-tailed t-test; P = 0.021 and P = 0.014, respectively)." (PMID 24019980, 2013). "In addition, CCND1 was frequently overexpressed in sarcoma (53%), 79% of which (42% of total sarcoma samples) showed a ≥10-fold increase in expression." (PMID 28377632, 2017). "In other previous studies, some genes (CCND1, CD109, NOS1, and ABLIM1) were found to be abnormally expressed in sarcomas, which can be used as prognostic markers or classification features for different sarcomas." (PMID 36619306, 2022). "We have shown that established Rh30 and RD sarcoma cell lines cultured in the presence of the tested PRMT inhibitors have decreased expression of TNC, NRP1, MYOF, EMP1, OLFML3 and CCND1 and increased expression of the GADD45G gene." (PMID 34360791, 2021). "In this subtype of sarcoma, CDKN2A firmly connects to MDM2, CCND1, PIK3CA, CDK4, CBX7, and less firmly to EGFR, and IL-6." (PMID 34359782, 2021). "Some of the genes identified already have a well-established connection to human sarcomas, including ORAOV1, SSX5, NKX2, XAGE1, MDK and CCND1." (PMID 30093970, 2018). "Positive expression of cyclin D1 and ErbB2/HER2 were seen in 44 cases (57.9%) and 0 case (0%) of sarcomas, respectively." (PMID 27249072, 2016). "We selected CCND1, MTA1, STEAP1, CDH2, CDH11, and CDT2 genes that are known to be involved in metastatic spread in several sarcoma subtypes, and their abnormal expression in tumors correlates specifically with poor prognosis in ES patients." (PMID 25008066, 2014). "High-grade endometrial stroma sarcomas show a strong and diffuse cyclin D1 positivity, are usually negative for CD10 and hormone receptors as well as melanocytic markers, and harbor the YWHAE–FAM22 genetic fusion in most cases." (PMID 31309284, 2020).
sarcoma (continued). "Our case had similar pathological features, but the absence of BCOR break-apart signals and cyclin D1 staining opposed the diagnosis of ZC3H7B-BCOR sarcoma." (PMID 32290854, 2020). "Furthermore, both the Cl2 and Cl3 subgroups, compared with the other four, showed an up-regulation of genes belonging to pathways involving tumor growth factor β (TGFβ), rat sarcoma (RAS), epidermal growth factor receptor (EGFR), and Cyclin D1." (PMID 25821127, 2015). "Amplifications of CDK4 and CCND1 (cyclin D1) were observed in 11% and 4% of the sarcomas respectively, but never in tumours with CDKN2 deletions." (PMID 7640224, 1995). "Cyclin D1, SATB2, TLE1, and CD10 are other immunostains that are not specific but helpful in considering a BCOR rearranged sarcoma, as noted in Cases 1 and 3 in this series." (PMID 40705064, 2025).
triple-negative breast carcinoma (34 papers, 2013 to 2026). An invasive breast carcinoma which is negative for expression of estrogen receptor (ER), progesterone receptor (PR), and human epidermal growth factor receptor 2 (HER2). "This study investigated contribution of CCND1 genotype to individual triple negative breast cancer susceptibility." (PMID 25520916, 2014). "Specifically, SPS have been shown to induce cell cycle arrest at the G0/G1 phase by down-regulating CDK4 and cyclin D1 while up-regulating p21 protein expression in triple-negative breast cancer cells (MDA-MB-231)." (PMID 40507156, 2025). "Based on previous reports of the cGAS/STING pathway being highly expressed and coupled to immune cell infiltration in triple-negative breast cancer with replication stress, we explored the expression of cyclin E1, cyclin D1 and c-Myc and immune infiltration." (PMID 39751944, 2025). "Activation of Akt-dependent NF–κB/Cyclin D1 pathway promotes triple-negative breast cancer cell proliferation." (PMID 37951919, 2023). "Knockdown of ZNF703 in triple-negative breast cancer cells was shown to inhibit the expression of cyclin D1, CDK4, CDK6, and E2F1 and upregulation of Rb1." (PMID 37686244, 2023). "Our study highlights GG genotype of CCND1 A870G playing a protective role in triple-negative breast cancer, as well as in early onset, early menarche and premenopausal Taiwanese women." (PMID 25520916, 2014). "Such valuable findings suggest CCND1 A870G (rs9344) as a predictive marker for triple negative breast cancer in Taiwanese women; the authors sincerely hope these help us fight the toughest subtype in clinical management." (PMID 25520916, 2014). "We found TGFβ to specifically up-regulate the expression of cyclin D1 in triple negative breast cancer cells." (PMID 23786849, 2013). "Both Jagged-1 and cyclin D1 levels correlated well with triple negative breast cancers, and Jagged-1 was found to play an important role in binding of Notch-1 to cyclin D1 promoter, an event necessary for cell cycle progression." (PMID 23533807, 2013). "In support of miR-17-5p’s tumor-suppressive role, recent bioinformatics and in vitro analysis revealed that levels of miR-17-5p are decreased in triple negative breast cancer cells resulting increase in CCND1 (cyclin D1) levels which is reason for uncontrolled proliferation." (PMID 29050357, 2017). "miR-1296 is downregulated in TNBC cells when compared to a non-tumorigenic breast cell line, and in the majority of human triple negative breast cancer samples when compared to normal breast samples In silico algorithms and sequence alignments identified the CCND1 oncogene as a potential target." (PMID 26799586, 2016). "With a collection of samples from a quite large population, we have found that the GG genotype in CCND1 A870G plays a protective role for triple-negative breast cancer, and in early onset (< 55 years), early menarche (<12.2 years) and premenopausal (<49 years) Taiwanese women." (PMID 25520916, 2014). "Still, no report investigates association of SNPs on CCND1 with triple negative breast cancer risk." (PMID 25520916, 2014). "Furthermore, using a panel of tumorigenic triple negative breast cancer cell lines, which exhibit differential responses to TGFβ in terms of cellular migration, we found cyclin D1 expression to correlate with p21 expression and to be required for TGFβ-induced cell migration." (PMID 23786849, 2013). "We had demonstrated marked reductions in phosphorylated ERK1/2 and cyclin D1, key effectors of the MAPK pathway, consistent with previous findings in cervical, gall-bladder, non-small-cell lung, and triple-negative breast-cancer systems." (PMID 41155954, 2025).
triple-negative breast carcinoma (continued). "In triple-negative breast cancer, high expression of ESM1 promotes tumor cell migration, proliferation and invasion through the Akt/NF-κB/Cyclin D1 signaling pathway." (PMID 37476182, 2023). "Our results suggest that inhibition of FKBP4 induces a cell cycle arrest in triple-negative breast cancer cells through down-regulation of the PI3K/Akt signaling activity, resulting in Cyclin D1 downregulation." (PMID 31660083, 2019). "Due to the role of cyclin D1 overexpression and PARP down expression in the sustenance of cancerous cells and their relationship with AKT 1 and p110α, inhibiting AKT 1 and p110α leads to augmented radiosensitivity in triple-negative breast cancer cells." (PMID 39539450, 2024). "Instead, the downregulation of X-linked inhibitor of apoptosis (XIAP) and survivin, two pro-survival proteins, under Rac inhibition by NCS23766 was shown to promote cell death in triple-negative breast cancer cells regardless of Bcl2 and cyclin D1 expression." (PMID 37316799, 2023).
renal carcinoma (32 papers, 2004 to 2026). A carcinoma arising from the epithelium of the renal parenchyma or the renal pelvis. "Common genetic variants at the 11q13.3 renal cancer susceptibility locus influence binding of HIF to an enhancer of cyclin D1 expression." (PMID 23690926, 2013). "Indeed, a genetic variant at chromosome 11q13.3 is associated with a predisposition to renal cancer by permitting HIF2α binding to a cyclin D1 enhancer." (PMID 29938199, 2018). "For example, PDE5 inhibition activates PKG, which reduces cyclin D1 (a cell cycle promoter) and elevates p21 (a cell cycle inhibitor), leading to apoptosis and suppressed proliferation in renal cancer cells." (PMID 40304310, 2025). "Studies have shown that miR-21 plays a role in the transcription of cyclin D1, and by inhibiting cyclin D1 mRNA expression, miR-21 Sponge effectively controls renal cancer cell proliferation through the activation of cyclin D1/CDK4 activity." (PMID 39114567, 2024). "Regarding the role of HIF2α in regulating the cell cycle machinery, cyclin D1 is another HIF2α target found specifically in renal cancers." (PMID 29938199, 2018). "Earlier studies showed that activated NF-κB binds to the cyclin D1 promoter, stimulating its expression, and that NF-κB controls miR-21-induced transcription of cyclin D1 in renal cancer cells." (PMID 27811358, 2016). "That many of the currently known renal cancer-associated SNPs (EPAS1, CCND1 and MYC/PVT1) can be linked to modulation of a single pathway (that is, the HIF pathway) is striking and to our knowledge unique in tumour biology." (PMID 27774982, 2016). "For example, HIF-2α is necessary to maintain tumour growth in RCC4 renal carcinoma cells, potentially via regulation of the cell cycle regulatory proteins TGFα and cyclin D1." (PMID 20637078, 2010). "PTPRZ1 knockdown could reduce the number of nuclear β-catenin and inhibit cell proliferation, as well as reduce target genes cyclin D1 and c-myc expressions in renal cancer." (PMID 35251170, 2022). "This suggests that PECAM1/CD31 and CCND1 could be used as indicators for the early diagnosis of renal cancer." (PMID 31850854, 2019). "Finally, to investigate early events in renal cancer, we screened for the hub genes CCND1 and PECAM1/CD31." (PMID 31850854, 2019). "In renal cancer, CACYBP overexpression reduces Cyclin D1 levels through β-catenin degradation, thereby inhibiting cell growth and tumorigenicity—further supporting its tumor-suppressive role." (PMID 40167359, 2025). "Cell cycle arrest can be induced by LGK974 by downregulating cyclin D1, c-Myc, MMP9, and MMP2 in renal cancer cells." (PMID 37763649, 2023). "A study performed on human renal cancer cell line treated with metformin, indicated that metformin may induce cell cycle arrest by up-regulating the level of miR-34a, decreasing the level of cyclin D1 expression and enhancing cyclin-dependent kinase inhibitor 1B (p27Kip1) expression." (PMID 33849540, 2021). "As a result of NFκB activation, the expression of cyclin D1 and CDK4 are increased as observed in renal cancer patients." (PMID 33849540, 2021). "We examined the expression of cytoplasmic β-catenin and Wnt target genes in renal cancer cells after treatment with LGK974, including the protein expression level of cyclin D1 and c-Myc and the RNA expression level of MMP9 and MMP2." (PMID 32104684, 2020). "Our previous study also demonstrated that DACH1 inhibited cyclin D1 expression and inversely correlated with PCNA in renal cancer cells or blocked cell proliferation through a c-Jun DNA-binding partner." (PMID 27888806, 2016). "The cyclin D1 and related cell cycle protein RB and CDK4 were measured in cultured renal cancer cell lines." (PMID 25322986, 2014).
renal carcinoma (continued). "Unlike, some other genes involved in renal cancer proliferation, such as cyclin D1 (CCND1), transforming growth factor alpha (TGFA) and the amino acid carrier SLC7A5 are preferentially induced by HIF2α." (PMID 33321829, 2020). "In contrast, Maher's group used an array of 558 genes and found CCND1 upregulated in a VHL mutant renal cancer cell line (RCC4), but it was not regulated by hypoxia." (PMID 15026807, 2004).
parathyroid adenomas (30 papers, 2007 to 2025). "So, promoter hypermethylation is associated with down-regulation of CCND1 regulatory genes in sporadic parathyroid adenomas." (PMID 28600574, 2017). "The underlying molecular mechanisms for development of parathyroid adenoma are not completely understood, but the role of Cyclin D1 (encoded by the CCND1 gene) in parathyroid tumorigenesis is well established." (PMID 28600574, 2017). "Parathyroid adenomas are benign, relatively indolent neoplastic lesions characterized by a low mitotic index, but activating mutations in proliferation-inducing oncogenes such as cyclin D1 have been shown to occur in 20–40% of sporadic PHPT tumors." (PMID 36992820, 2023). "In addition to MEN1 and CCND1, other genes that participate in the development of parathyroid adenoma include those encoding cyclin-dependent kinase inhibitors, along with CTNNB1, EZH2, ZFX, GCM2, and CASR." (PMID 30832348, 2019). "The CCND1 gene was first identified in parathyroid adenomas due to the presence of a centromeric inversion of chromosome fourteen." (PMID 37951919, 2023). "The overexpression of the oncogene cyclin D1/PRAD1 is observed in 20% to 40% of parathyroid adenomas, and it is considered a molecular driver of sporadic adenomas." (PMID 35628190, 2022). "The target-PPI included differentially methylated genes as well as parathyroid adenoma susceptible genes (CDC73, MEN1, CCND1, RET)." (PMID 35879975, 2022). "According to various studies, CDC73, MEN1, CCND1, and RET were shown to be parathyroid adenoma susceptible genes." (PMID 35879975, 2022). "Genes that have been linked to the pathogenesis of sporadic parathyroid adenomas include MEN1, cyclin D1/PRAD1 and cyclin-dependent kinase inhibitors (CDKI), such as CDKN1B/p27." (PMID 32331456, 2020). "To date, MEN1 and CCND1 (respectively, a tumor suppressor and a proto-oncogene) are the most solidly established molecular drivers of sporadic parathyroid adenoma." (PMID 30832348, 2019). "The relative expressions of the CDKN2A, CDKN2B and RASSF1A genes were analysed by quantitative RT-PCR and were related to the cyclin D1 (CCND1) expression in parathyroid adenoma samples." (PMID 28600574, 2017). "The gene encoding cyclin D1, CCND1, located in chromosome 11q13, was initially designated PRAD1 (parathyroid adenomatosis 1) since it was cloned from DNA from a parathyroid adenoma." (PMID 22567348, 2011). "The hormonal regulatory defect in parathyroid adenomas can be both primary and secondary to a defect in cellular - growth control indicated by cyclin D1 oncogene overexpression." (PMID 21176227, 2010). "Cyclin D1 overexpression is a feature of typical parathyroid adenomas as had been suggested by early DNA studies." (PMID 19032735, 2008). "They think that over expressed cyclin D1 plays a role in the pathogenesis of a much larger proportion of parathyroid adenomas than previously assumed." (PMID 19032735, 2008). "In a small fraction of parathyroid adenomas, overexpression is due to activation of the CCND1 gene by pericentromeric inversions of Chromosome 11, involving the parathyroid hormone (PTH) promoter." (PMID 18044981, 2007). "PHPT is characterized by autonomous secretion of parathyroid hormone (PTH) by parathyroid tissues, and about 80-85% of cases originate from monoclonal parathyroid adenomas, the molecular mechanism of which involves cyclin D1 (CCND1/PRAD1) overexpression and the development of Wnt/β-cyclin." (PMID 41210508, 2025). "Cyclin D1 (also located at 11q13) is overexpressed in 10–40% of parathyroid adenomas due to aberrant promoter methylation of different cyclin-dependent kinase inhibitors (CDKIs), while rearrangement of the Cyclin D1 gene (CCND1) occurs in up to ~ 10% of parathyroid adenomas." (PMID 38108848, 2024).